SHANK2 (SH3 and multiple ankyrin repeat domains 2)
Diseases named in the same sentence as SHANK2 in open-access papers (continued):
Sharing a sentence is not in itself a finding about the gene and the disease.
tumor (21 papers, 2010 to 2025). "For instance, in renal cell carcinoma, SHANK2 expression has been linked to tumor growth and metastasis, indicating its potential as a biomarker for aggressive disease." (PMID 39397895, 2024). "Similarly, in breast cancer, alterations in SHANK2 expression have been associated with changes in cellular adhesion and migration, implicating its involvement in tumor invasiveness." (PMID 39397895, 2024). "SHANK2 might cooperate with EMS1 to encode cytoskeleton-associated proteins implicated in tumor cell motility and invasiveness in OSCC." (PMID 28852427, 2017). "Laboratory-based experiments are necessary to delineate the specific pathways through which SHANK2 exerts its effects on tumor cells." (PMID 39397895, 2024). "When injected into nude mice, SHANK2 depletion also severely reduced the ability to form tumor in vivo." (PMID 32661924, 2021). "Our results suggest SHANK2 is such an evolutionarily conserved regulator of Hippo pathway, commonly amplified in human cancer and potently promotes tumor formation." (PMID 32661924, 2021). "SHANK2 is located at the 11q13 tumor amplicon, a relatively large amplicon containing several focal amplification peaks." (PMID 32661924, 2021). "Both our analysis of the COSMIC dataset and the Broad cancer gene copy number analysis of the 11q13 tumor amplicon clearly indicates a selection for SHANK2 amplification." (PMID 32661924, 2021). "To assess if the most common gains resulted in increased protein expression of target genes, we assessed Shank2 and cortactin immunoreactivity in normal and tumor esophageal tissues." (PMID 32252688, 2020). "Although research on SHANK2 in cancer is still emerging, studies in various malignancies suggest that it may play a role in tumor development and progression." (PMID 39397895, 2024). "Whole exome sequencing results revealed that such EV-DNA carried tumor-specific genetic mutations, including those occurring on known oncogenes and tumor suppressor genes in neuroblastoma (ALK, CHD5, SHANK2, PHOX2B, TERT, FGFR1, and BRAF), and represented the entire exome." (PMID 39402599, 2024). "Understanding whether SHANK2 expression levels correlate with tumor grade, patient survival, or treatment responsiveness could offer new avenues for prognostication and potentially identify novel therapeutic targets." (PMID 39397895, 2024). "lnc-FGF3-4 may promote tumor cell proliferation by upregulating SHANK2 to inhibit the Hippo signaling pathway." (PMID 37538124, 2023). "SHANK2 is the most frequently amplified gene on 11q13, a major tumor amplicon in human cancer." (PMID 35456975, 2022). "The expression of SHANK2 was reduced in advanced-stage tumours in the KIRC and KIRP datasets (p < 0.001 and p = 0.025, respectively), and low SHANK2 expression levels were significantly associated with a poor survival of patients (p < 0.001 and p = 0.041, respectively)." (PMID 36231770, 2022). "Interestingly, a mammalian homolog of Prosap, SHANK2, is the most frequently amplified gene on 11q13, a major tumor amplicon in human cancer." (PMID 32661924, 2021). "The results showed that SHANK2 also significantly enhanced tumor growth in this model." (PMID 32661924, 2021). "Recurrent SVs in CSMD1, WWOX, ERC1, PDE4D and SHANK2 were also identified in five tumor samples." (PMID 32617189, 2020). "We further asked whether SHANK2 can promote tumor formation by endogenous cells in mice." (PMID 32661924, 2021). "Further studies in multiple human cell lines confirmed that SHANK2 overexpression causes deregulation of Hippo signaling through competitive binding for a LATS1 activator, and as a potential oncogene, SHANK2 promotes cellular transformation and tumor formation in vivo." (PMID 32661924, 2021). "To further understand this, we performed a detailed analysis of the SHANK2 and Cyclin D1 amplification status in COSMIC tumor samples." (PMID 32661924, 2021).
tumor (continued). "Finally, SH3 and multiple ankyrin repeat domains 2 (SHANK2), which binds the SH3 domain of cortactin and is thereby thought to promote cell motility at growth cones of neurons, is 51-fold up-regulated in the tumor." (PMID 20174472, 2010).
cancer (16 papers, 2008 to 2024). A tumor composed of atypical neoplastic, often pleomorphic cells that invade other tissues. "Together, SHANK2 plays important roles in cancers; however, its underlying mechanisms of action vary greatly depending on the cellular contexts." (PMID 36231770, 2022). "Despite these findings, the mechanisms by which SHANK2 influences cancer biology remain largely undefined." (PMID 39397895, 2024). "The SH3 And Multiple Ankyrin Repeat Domains 2 (SHANK2) gene, known for its role in synaptic architecture and function, has recently attracted attention for its potential involvement in cancer." (PMID 39397895, 2024). "SHANK2 is a recently reported Hippo pathway regulator, amplified in human cancer and potently promotes cancer." (PMID 35468874, 2022). "To more clearly estimate the significance of SHANK2 amplification in human cancer, we compiled gene amplification status for all human coding genes based on the COSMIC dataset." (PMID 32661924, 2021). "In multiple human cancer cell lines that overexpress SHANK2, upon SHANK2 knockdown, YAP phosphorylation was restored at high cell density, and YAP were sequestered in cytoplasm under such conditions." (PMID 32661924, 2021). "In their analysis, focal amplification of 11q13.3 was observed in 37% of cancer samples and 79% of these samples showed overexpression of SHANK2." (PMID 32661924, 2021). "Such a striking amplification status for SHANK2 suggests that it’s a very prominent genomic event for human cancer." (PMID 32661924, 2021). "To further understand the relative significance of SHANK2 amplification in human cancer, we referenced the COSMIC (Catalogue Of Somatic Mutations In Cancer) database, which provided gene amplification information of approximately 15,000 cancer samples." (PMID 32661924, 2021). "Considering the expression pattern of SHANK2 and the knockout mice phenotype, it is possible that SHANK2 is necessary for growth only in cancer cells that overexpress SHANK2, and that most human normal adult tissues do not utilize SHANK2 for growth." (PMID 32661924, 2021). "Among the 11q13-amplified cancer samples that carry amplification of SHANK2 and/or Cyclin D1, 233 amplified both SHANK2 and Cyclin D1, 412 amplified only SHANK2 and 50 amplified only Cyclin D1." (PMID 32661924, 2021). "Among the three mammalian homologs of Prosap, SHANK2 is the most prominently amplified gene in human cancer." (PMID 32661924, 2021). "Taken together, these results suggest that SHANK2 is an evolutionarily conserved Hippo pathway regulator, commonly amplified in human cancer and potently promotes cancer." (PMID 32661924, 2021). "Taken together, these results indicate SHANK2 is an evolutionarily conserved regulator of Hippo signaling with oncogenic function in human cancer." (PMID 32661924, 2021). "In cancer cell lines with deregulated Hippo pathway, depletion of SHANK2 restores Hippo signaling and ceases cellular proliferation." (PMID 32661924, 2021). "Our study for the first time illustrated oncogenic function of SHANK2, one of the most frequently amplified gene in human cancer." (PMID 32661924, 2021). "Lastly, we examined cancer cell lines that overexpress SHANK2 and exhibit deregulated Hippo signaling." (PMID 32661924, 2021). "Taken together, our study for the first time assigned an oncogenic function for SHANK2, one of the most prominently amplified genes in human cancer." (PMID 32661924, 2021). "Together with our experimental data, this further strengthens a role for SHANK2 in promoting cancer." (PMID 32661924, 2021). "Alterations in the microRNA machinery have been described in various cancers; therefore, we further analyzed the regulatory effect of miR-137 on Shank2 expression in mouse primary hippocampal neurons." (PMID 29665782, 2018). "SHANK2 is upregulation in cancer cells and can suppress the Hippo signaling pathway." (PMID 37538124, 2023).
cancer (continued). "Given that many cancers amplify SHANK2, this finding may help understand how cancer cells managed to escape from contact inhibition." (PMID 32661924, 2021). "Based on these two studies, we hypothesized that in cancer cells, overexpressed SHANK2 interacts with and sequesters ARHGRF7 away from LATS1, which then leads to reduced LATS1 activity and enhanced cell growth." (PMID 32661924, 2021). "Newly identified oncogenes in the Hippo pathway such as Gq/G11 and SHANK2 may also represent potential PROTAC targets for cancer treatment." (PMID 34150758, 2021). "Importantly, in addition to amplification, SHANK2 is also overexpressed in multiple types of human cancer." (PMID 32661924, 2021). "Such correlations provide further support to our hypothesis that SHANK2 positively regulates YAP in cancer." (PMID 32661924, 2021). "Considering that in human SHANK2 is not expressed in most adult tissues, such a mechanism may be more relevant to pathological conditions, when SHANK2 is amplified in cancers." (PMID 32661924, 2021). "About five-fold more cancer samples exhibit SHANK2 amplification compared to SHANK1 and SHANK3." (PMID 32661924, 2021). "Interestingly, judging by the number of cancer samples carrying gene amplification, SHANK2 was more frequently amplified than many well-established oncogenes." (PMID 32661924, 2021). "Given that in human cancer, SHANK2 is the most frequently amplified gene outside of the Myc amplicon, it may provide explanation for how a significant portion of human cancer disables Hippo signaling and evades contact inhibition." (PMID 32661924, 2021). "This suggests that there are separate selective pressures for SHANK2 and Cyclin D1 amplification, and they may both promote cancer." (PMID 32661924, 2021). "Most miR-137 targets have been investigated in cancer cell lines and only 13 miR-137 target genes (including SHANK2) have been confirmed in neuronal cells; therefore, some of the confirmed targets may not be miR-137 targets in the brain." (PMID 29665782, 2018). "Such drugs could be useful in treating cancers that depend on SHANK2." (PMID 32661924, 2021). "Therefore we focused on the potential role of SHANK2 as a growth-promoting gene in human cancer." (PMID 32661924, 2021). "Interestingly, one of Prosap’s mammalian homologs, SHANK2, is highly amplified in human cancer." (PMID 32661924, 2021). "As a novel oncogene, SHANK2 could potentially provide a new target for treating cancer." (PMID 32661924, 2021). "Several other recently identified upstream and downstream regulators of Hippo signaling, including FAT1, SHANK2, Gq/11, and SWI/SNF complex, are more commonly dysregulated in human cancer at the genomic level." (PMID 34150758, 2021). "SHANK2 and CTTN are co-amplified in several cancers, these proteins interact functionally together and are involved in cell motility." (PMID 32252688, 2020). "More importantly, across the human cancer genome, SHANK2 is the most frequently amplified gene that is not located within the Myc amplicon." (PMID 32661924, 2021). "In BrCa, this combined analysis indicated that the events are related to CCND1 amplifications, despite the frequent events in sizeable genes TEMN4 and SHANK2 of which their fusion transcripts are not driving cancer." (PMID 34891161, 2021). "It is worth noticing that the number of cancer samples with SHANK2 amplifications way exceeds those with YAP1 amplification, FAT1 deletion, and NF2 deletion, indicating a previously unnoticed role of SHANK2 as a major oncogene." (PMID 34150758, 2021). "Strikingly, out of the 100 most frequently amplified genes in human cancer, SHANK2 is the only exception that does not reside on chromosome 8q." (PMID 32661924, 2021). "Immunoblot analysis of various mouse tissues confirmed the lack of expression of SHANK2 in most non-neuron tissues, including bone marrow and intestine, two major sites of toxicities for cancer treatment." (PMID 32661924, 2021).
cancer (continued). "This suggests that during cancer formation, SHANK2 is selected independent of Cyclin D1." (PMID 32661924, 2021). "Prior to our study, there were no reports demonstrating SHANK2’s oncogenic role in human cancer." (PMID 32661924, 2021). "In many cases, after SHANK2 depletion no cancer cell mass was discovered in vivo." (PMID 32661924, 2021). "Given the recent finding that 11q13 amplification does not sensitize cancers to CDK4/6 inhibitor, SHANK2 may present an alternative target for treating cancers with 11q13 amplification." (PMID 32661924, 2021).
neurological diseases (7 papers, 2017 to 2025). "SHANK2, a scaffold protein primarily studied in neurological disorders, has recently been implicated in immune modulation and cellular signaling." (PMID 41142802, 2025). "Despite the relevance of SHANK2 in human neurological disorders and the link between cellular SHANK2 expression and behavioral phenotypes, protein expression studies have been largely performed in rodents." (PMID 37953224, 2023).
psychiatric disorder (7 papers, 2012 to 2022). A disorder characterized by behavioral and/or psychological abnormalities, often accompanied by physical symptoms. "Finally, the experiments using Shank2-deficient mice clearly demonstrate that our VR paradigms are immediately applicable to studies of developmental and psychiatric disorders." (PMID 28484738, 2017). "SHANK2 (also known as ProSAP1) is the second member of the Shank protein family and is involved in neurodevelopmental and psychiatric disorders." (PMID 32607230, 2020). "Furthermore, we identified a SHANK2 splice site mutation in a control female without any apparent psychiatric disorders." (PMID 22346768, 2012).
brain disorder (2 papers, 2022 to 2023). A disease affecting the brain or part of the brain. "Numerous studies on the functions of Shank2 and Shank3, including those using mouse genetic approaches, have provided substantial insights into the mechanisms underlying Shank2- or Shank3-related brain disorders." (PMID 36311023, 2022).
infection (2 papers, 2017 to 2018). The state of being infected such as from the introduction of a foreign agent such as serum, vaccine, antigenic substance or organism. "Similarly, infection with the shShank2 viruses effectively reduced the levels of Shank2." (PMID 29250591, 2017).
SHANK2 also shares sentences with these, for which no sentence is quoted: fragile X syndrome (4 papers); attention deficit-hyperactivity disorder (3); cardiomyopathy (2); diabetes (2); lung cancer (2); type II diabetes (2); amyotrophic lateral sclerosis (1); Asperger syndrome (1); asthma (1); cardiac hypertrophy (1); cognitive decline (1); colitis (1); COVID-19 (1); deafness (1); emphysema (1); fungal infection (1); genetic diseases (1); hepatocellular carcinoma (1); Huntington disease (1); Hypertension (1); Malan syndrome (1); melanoma (1); microcephaly (1); migraine (1); Mild intellectual disability (1); muscular dystrophy (1); neurodegenerative disease (1); obsessive-compulsive disorder (1); oligodendroglioma (1); oral cancer (1).
A further 8 diseases each share a sentence with SHANK2 in 1 paper.